IL18 (interleukin 18)
Diseases named in the same sentence as IL18 in open-access papers (continued):
Sharing a sentence is not in itself a finding about the gene and the disease.
osteoarthritis (24 papers, 2011 to 2025). A noninflammatory degenerative joint disease occurring chiefly in older persons, characterized by degeneration of the articular cartilage, hypertrophy of bone at the margins and changes in the synovial membrane. "has unveiled that inhibiting the Nrf2/HO‐1 pathway results in increased activation of the NLRP3 inflammasome, along with upregulation of IL‐1β and IL‐18 expression in osteoarthritis." (PMID 41378869, 2025). "The production of two inflammatory cytokines, IL-18 and IL-1β, is correlated with the presence of uric acid in the synovial fluid; among these, IL-18 was found to correlate with osteoarthritis progression." (PMID 38548957, 2024). "Serum and synovial fluid levels of IL-18 were higher in RA than in osteoarthritis patients and correlated with disease activity as assessed by the Disease Activity Score 28 (DAS28)." (PMID 37415987, 2023). "IL-18 mRNA and protein are expressed in the rheumatoid synovium with significantly higher levels than in osteoarthritis tissues." (PMID 37415987, 2023). "Synovial tissue IL-18 mRNA levels were significantly higher in AOSD patients than in osteoarthritis patients, whereas TNF-α and IL-8 mRNA levels were higher in RA patients than in AOSD patients." (PMID 37415987, 2023). "Some of the cytokines shown to increase in osteoarthritis are IL-18, TGFβ1, IL-1 receptor (IL-1R), and IL-1 alpha (IL-1α)." (PMID 32189997, 2020). "Interleukin 18 (IL-18) promotes inflammation and apoptosis in chondrocytes, thereby contributing to the development and progression of osteoarthritis (OA)." (PMID 32182210, 2020). "Osteoarthritis (OA), the most common joint disease worldwide, is characterized by low-grade inflammation and increased levels of cytokines, including IL-1β and IL-18." (PMID 33014529, 2020). "A study conducted among patients with osteoarthritis showed that IL-1β, IL-6, IL-8, IL-18, IL-17, IL-22, and transforming growth factor-beta 1 (TGFβ1) were increased in the inflamed synovium tissues compared to the noninflamed tissues." (PMID 32189997, 2020). "Shao and L. Feng also reported the increase gene expression of IL-18 and it ́s receptor in RA patients as compared to osteoarthritis patients considered as control group." (PMID 31258598, 2019). "Therefore, inhibiting the expression of inflammation related genes IL-6, IL-1 β, and IL-18 is beneficial for the remission of osteoarthritis." (PMID 34421623, 2021). "Interestingly, females with osteoarthritis show higher levels of IFN-γ, IL-3, IL-8, IL-18, and TNF-β, and other factors that stimulate macrophages compared to osteoarthritis men." (PMID 39439003, 2024). "The pathogenesis of RA involves many immune cells and cytokines, including interleukin-1 (IL-1), interleukin-6 (IL-6), interleukin-18 (IL-18), and tumor necrosis factor (TNF) as the main pro-inflammatory cytokines, which induce inflammatory response and osteoarthritis injury." (PMID 35833125, 2022). "In conclusion, l-carnitine augmented the probenecid’s anti-inflammatory effect to attenuate MIA-induced osteoarthritis in rats by provoking the miRNA-373 level and inhibiting the P2X7/NLRP3/NF-κB milieu, leading to the suppression of serum inflammatory cytokines: IL-1β, IL-18, IL-6, and TNF-α." (PMID 37994991, 2024).
allergic disease (23 papers, 2006 to 2025). An immune response that occurs following re-exposure to an innocuous antigen, and that requires the presence of existing antibodies against that antigen. "Previous studies show IL‐18 critical role in eosinophil development and transformation from naïve to pathogenic eosinophils in patients with allergic diseases." (PMID 37186423, 2023). "A number of allergic diseases, including AD, have been associated with elevated serum or tissue levels of IL-18." (PMID 36142206, 2022). "This prominent feature of IL-18 can explain the mechanism for infection-associated allergic diseases." (PMID 29731751, 2018). "Currently, IL-18 genetic polymorphisms have been postulated to be implicated in the development of allergic disease." (PMID 24995282, 2014). "In the subgroup analysis by the type of allergic disease, we only found significant association between IL-18 −607C/A polymorphism and AA under heterozygous comparison (AC versus CC: OR = 0.82, 95% CI = 0.69–0.98, P = 0.03)." (PMID 24995282, 2014). "In the future, more large-scale studies should be carried out to confirm or refute the relationship between IL-18 polymorphisms and the risk of allergic disease." (PMID 24995282, 2014). "Genetic polymorphisms of the human IL18 gene have been associated with a wide variety of diseases, including allergic diseases and inflammatory diseases." (PMID 16563174, 2006). "This unique function of IL-18 contributes to infection-associated allergic diseases." (PMID 29731751, 2018). "Since tryptase is exclusively released from mast cells upon degranulation and mast cells are the primary effector cells of allergy, we anticipated that elevated IL-18 level may be caused by tryptase." (PMID 27069315, 2016). "Recent studies have suggested that IL-18 polymorphisms may be associated with the risk of allergic disease; however, individually published results are inconclusive due to small sample sizes." (PMID 24995282, 2014). "Our meta-analysis showed that IL-18 −607C/A and −137G/C polymorphisms might be involved in the etiology of allergic disease, revealing a significant protective role or decreased risk towards AA and AD, respectively." (PMID 24995282, 2014). "Recent studies have suggested that IL-18 −607C/A and −137G/C polymorphisms may be associated with the risk of allergic disease; however, individually published results are inconclusive." (PMID 24995282, 2014). "Large quantities of evidence support the hypothesis that IL-18 genetic polymorphisms may cause the abnormal expression of IL-18, which is responsible for mediating the T-cell regulation, thereby leading to the pathological development of allergic disease." (PMID 24995282, 2014). "Therefore, we performed a meta-analysis to clarify whether IL-18 −607C/A and −137G/C polymorphisms were associated with the risk of allergic disease." (PMID 24995282, 2014). "IL-18 has been reported to be elevated in allergic diseases and to promote mast cell activation, eosinophil recruitment and IgE production in experimental systems." (PMID 41476961, 2025). "It operates by inhibiting the activities of NLRP3, caspase-1, and ASC, thereby reducing the secretion of IL-1β and IL-18 in various allergic diseases." (PMID 39131161, 2024). "Recent studies in humans and mice strongly suggest a link between the NLRP3 inflammasome, IL-1β, and IL-18, and the development of allergic diseases." (PMID 39131161, 2024). "Recently, accumulating evidence from human and mouse experiments has demonstrated the critical involvement of the NLRP3 inflammasome, IL-1β, and IL-18 in the development of allergic diseases." (PMID 38277371, 2024). "OLT1177’s specific inhibition of NLRP3 inflammasomes offers a promising therapeutic approach to prevent the release of pro-inflammatory factors IL-1β and IL-18, potentially benefiting the treatment of allergic diseases." (PMID 39131161, 2024).
allergic disease (continued). "IL-1β and IL-18 can stimulate the differentiation and proliferation of Th2 cells and exacerbate related allergic reactions." (PMID 37817225, 2023). "IL-18 was involved with varied of diseases, such as allergy, kidney diseases, metabolic disorders, cancer, and organ transplantation." (PMID 34367377, 2021). "Induction of mast cell accumulation by IL-18 is an important finding as mast cells are primary effecter cells of allergy, and substantial quantity of this cell type is required to initiate pathological damage of the involved tissue." (PMID 27069315, 2016). "All of these findings suggest that IL-18 plays important roles in both antiallergic and allergy-promoting effects." (PMID 24995282, 2014). "More recently, positive relationship has been found between IL-18 levels in the lesion or circulation and allergic diseases, such as AA, AR, and AD." (PMID 24995282, 2014). "A surfeit of IL-18 has been found in patients with allergic diseases, including AA, AD, and AR, in which a predominance of Th1 cells is significant." (PMID 24995282, 2014). "There are several reports that IL-18 plays a pathogenically important role in chronic inflammatory conditions of epithelial organs (such as skin, gut, and kidney) and allergic diseases." (PMID 24490166, 2013). "Interleukin 18 seems to be involved in human allergic diseases such as atopic dermatitis (AD), bronchial asthma, and rhinitis." (PMID 23282478, 2008). "Besides, IL-18 alone can initiate a Th2 response from basophils and mast cells to induce an allergic reaction." (PMID 36354688, 2022). "IL-18 alone can trigger the Th2 response resulting in an allergic reaction." (PMID 36354688, 2022). "Taken together, these studies show that IL-18 may be having both allergy-promoting and antiallergic functions." (PMID 24995282, 2014). "Subgroup analyses according to ethnicity revealed similar results, suggesting that the environment they lived in did not play an obvious role in the association between IL-18 polymorphisms and the risk of allergic disease." (PMID 24995282, 2014). "IL-18 has various pro-inflammatory effects besides the induction of IFN-γ production, and IL-18 may be associated with various pathologies such as infections, allergic diseases, and tumor immunity." (PMID 33732720, 2021). "Therefore, BCL6 might be a key regulator of IL-18 production by macrophages in allergic diseases." (PMID 23282478, 2008).
lung disease (23 papers, 2013 to 2025). "MAS825, an IL-1 and IL-18 neutralizing antibody, was trialled in a case of Still’s-associated lung disease." (PMID 41281302, 2025). "On the other hand, one of the main risk factors for the lung disease in SJIA is strikingly high levels of serum IL-18." (PMID 38183096, 2024). "This is consistent with increased levels of circulating IL‐18 both in experimental alveolar hypoxia and in patients with hypoxic lung diseases." (PMID 39034131, 2024). "Some cytokines, for example, MCP-1/CCL2 and SDF-1 alpha were associated with the diagnosis of RA-ILD, and IL-18 levels were associated with a diagnosis of RA-ILD and a more marked progression of lung disease." (PMID 37047772, 2023). "The patient had very high IL-18 levels consistent with the phenotype of young children who do not respond to biologics and are at risk of lung disease." (PMID 38183096, 2024). "Mitochondrial ROS also activate the NLRP3 inflammasome in multiple pulmonary diseases, consistent with an inflammation model that includes our IL18-pathway and HK1 results, ROS-related proinflammatory responses to lung capillary pressure, and evidence of alveolar epithelial injury/SDB interactions." (PMID 34446064, 2021). "Moreover, NLRP3-derived cytokines (e.g., IL-1β, IL-18) appear to be the main inducers of a cytokine cascade (involving IL-23, IL-17, IL-26, IL-6, IL-13, and IL-5) that is responsible for the development of pulmonary diseases in morbidly obese subjects." (PMID 35806353, 2022). "Previous studies have shown that macrophages are a known source of IL-18 which is processed by NLRP3 and contributes to acute lung inflammation in multiple models including cigarette smoke-induced lung disease." (PMID 40777291, 2025). "In regards to such a supposition, the co-expression of the proteins of the IL-18/IL37 signalling complex and IP-10 should be further analysed in patients with pulmonary disease including those with pulmonary disease other than TB." (PMID 31821340, 2019). "Herein, we identify specific cytokines, such as IP-10, IL-18, TNF-α, and ISG54, that are elevated in hMPV mediated lung disease." (PMID 27171557, 2016). "The present study revealed that IL-8, IL-10, IL-18, TNF-α, and IP-10 are significantly correlated with pulmonary disease activity and global disease activity." (PMID 24800252, 2014). "As for the cytokine profile, patients with RA-ILD and the progression of lung disease had higher values of IL-1 alpha, IL-18, and MCP-1/CCL2 than those whose disease did not progress." (PMID 37047772, 2023). "SJIA patients with lung disease have a dramatic increase of circulating IL-18, at a higher level than sJIA without this complication." (PMID 37048785, 2023). "We previously reported that in vivo overexpression of IL-18 alone is not sufficient to elicit lung disease, since lymphocyte-specific IL-18 B6 Tg mice, and skin-specific IL-18 B6 Tg mice did not exhibit pulmonary inflammation or emphysema." (PMID 23382928, 2013). "Therefore, it appears that lung diseases are promoted by the secretome from dysfunctional adipose tissue, the altered adipokine profile of which drives NLRP3 inflammasome activation and subsequent production of IL-1β and IL-18." (PMID 35806353, 2022).
ulcerative colitis (23 papers, 2010 to 2025). An inflammatory bowel disease involving the mucosal surface of the large intestine and rectum. "Loss of goblet cells, specialized epithelial cells that secret mucins, is a hallmark of ulcerative colitis, and IL-18 is important for the breakdown of the mucosal barrier integrity." (PMID 37215126, 2023). "Previous data suggest that ulcerative colitis is improved by inhibiting the CCL2/NF-κB/IL-18 pathway, thereby preserving colon function." (PMID 39568749, 2024). "The NLRP3 inflammasome drives release of pro‐inflammatory cytokines including interleukin (IL)‐1β and IL‐18 and is a potential target for ulcerative colitis (UC)." (PMID 37962000, 2023). "Collectively, the present data demonstrate that DAPA represents an attractive approach to ameliorating ulcerative colitis through inhibiting MCP1/NF-κB/IL-18 pathways, thus preserving colon function." (PMID 35052720, 2021). "It is therefore suggested that IL-18 targeting may prevent the pathologic breakdown of the mucosal barrier in human ulcerative colitis." (PMID 39769266, 2024). "They proposed that a strict equilibrium of epithelial IL-18 signaling must be maintained and suggested that IL-18 targeting may prevent the pathologic breakdown of the mucosal barrier in human ulcerative colitis." (PMID 39769266, 2024). "Additionally, NLRP3 inflammasome has been investigated relatively to having a role in the pathogenesis of ulcerative colitis, as it is responsible for activating the expression of caspase-1, producing IL-1β and IL-18 and starting the inflammatory process." (PMID 35745756, 2022). "Moreover, the ability of MCC950 to suppress both translational and transcriptional IL-1β and IL-18 of canonical and noncanonical NLRP3 inflammasome in the colon may be promising in inflammatory intestinal diseases other than ulcerative colitis." (PMID 29872077, 2018).
fibrosis (22 papers, 2012 to 2026). the formation of excess fibrous connective tissue in an organ or tissue in a reparative or reactive process. "We postulate that sterile inflammation, including the release of TNFα, IL-1β, IL-18 and IL-6, leads to changes in the endothelial-epithelial barrier and induces chronic fibrosis." (PMID 36993804, 2023). "IL-18 has recently been identified as an important mediator of obstructive renal injury, stimulating both tubulointerstitial fibrosis and tubular epithelial cell apoptosis during obstruction independent of TGF-β1 production." (PMID 23077611, 2012). "Emerging candidate biomarkers for CKD progression include surrogates of tubulointersitital injury (NGAL, IL-18, KIM-1, EGF), tubulointerstitial fibrosis (MMP-9, PIIINP, TGF-β1, BMP-7), and inflammation (MCP-1, TNFR 1/2, suPAR)." (PMID 33108507, 2021). "Measuring IL-1β, IL-18, CTGF, and TNF-α in BAL fluid along with pulmonary function tests may enable early diagnosis of patients who will develop fibrosis." (PMID 41302962, 2025). "Taken together, our findings identify a pathomechanism whereby free or AM-bound IL-18 triggers proteolysis at PAJs through Cathepsin B, irrigating lungs with pre-made ECM which further activates myofibroblasts to trigger and perpetuate chronic fibrosis." (PMID 39747171, 2025). "Further, IL-18 transgenic (Tg) mice that lacked IL-17A and/or IL-13 had a significant decrease in airway fibrosis and mucus metaplasia." (PMID 39554494, 2024). "Alternately, airway fibrosis and mucus metaplasia increased significantly in IL-18 Tg mice that lacked IFN-γ." (PMID 39554494, 2024). "Soluble CD14, IL-18 and other immune activation mediators are produced in abundance in the liver in response to HCV and can act to perpetuate intrahepatic inflammation and progression of fibrosis and cirrhosis of the liver." (PMID 35482664, 2022).
injury (22 papers, 2014 to 2025). Damage inflicted on the body as the direct or indirect result of an external force, with or without disruption of structural continuity. "This is in accordance with previous studies that underlined the importance of IL-1β and IL-18 in mediating the PA-induced acute lung injury and activation of NLRP3 inflammasome." (PMID 36463179, 2022). "Treatment with IL-18BP, a natural IL-18 antagonist, significantly improved neurological recovery after traumatic brain injury." (PMID 39858411, 2024). "A previous study found that isoflurane exposure downregulated the pro‐inflammatory factors (such as IL‐18 and IL‐1β) in rats suffering from cerebral ischemia–reperfusion injury, and improved neuroinflammation and cognitive function." (PMID 38945806, 2024). "Consistently, the inhibition of the NLRP3 inflammasome, which activates caspase-1 to promote the maturation and release of IL-18, has also been shown to reduce inflammatory cytokines after traumatic brain injury." (PMID 39858411, 2024). "The adoptive transfer of N(IL-23+IL-18) neutrophils significantly increased the pathogenesis in a renal ischemia–reperfusion injury mouse model." (PMID 38137369, 2023). "Previous studies proved that IL-1β and IL-18 induced nerve injury and impaired the function of neurons." (PMID 37144237, 2023). "In fact, NLRP3 activation has been demonstrated to contribute to multiple diseases by increasing IL-1β and IL-18 secretion and amplifying the inflammatory response, including acute lung injury and acute liver failure." (PMID 32695257, 2020). "This is supported by the fact that synthetic PIF reduces the inflammasome response and NALP-3 induced IL-18 and IL-1β impact the pathogenesis of preeclampsia, preterm birth, and perinatal brain injury." (PMID 28704412, 2017). "Notably, caspase-1, IL-1β, and IL-18, the well-known markers of pyroptosis, which have been shown to be increased in other disease states such as lung injury, kidney inflammation, cardiomyopathy, and liver damage, were increased after Dox treatment." (PMID 33316945, 2020). "We focused on such acute complications, probably for the first time in the literature, using very sensitive markers of kidney injury (KIM-1, Il-18) as well as the fractional excretion of various ions as the indicators of renal tubules function." (PMID 35207193, 2022). "Furthermore, the increases in the pro-inflammatory cytokine, IL-18, and macrophage migration inhibitory factor (MIF) reported here have also previously been shown to increase their spinal cord expression following nerve injury, and have been implicated in contributing to sensory abnormalities." (PMID 25905723, 2015). "Interestingly, repeated intrathecal administration of both antagonists decreased the mRNA and/or protein levels of pronociceptive interleukins (i.e., IL-1beta, IL-6, IL-18) in the spinal cord, but only (±)-NBI-74330 decreased their levels in the dorsal root ganglia after nerve injury." (PMID 34681732, 2021).